MYD88 (MYD88 innate immune signal transduction adaptor)
Diseases named in the same sentence as MYD88 in open-access papers (continued):
Sharing a sentence is not in itself a finding about the gene and the disease.
colitis (continued). "Although the phenotype was rescued in the absence of Rip3 both in small and large intestine, only the colitis was dependent on MyD88 and TNF." (PMID 25346729, 2014). "For example, the spontaneous T-cell-mediated colitis observed in IL-10−/− mice did not arise in MyD88−/−IL-10−/− mice." (PMID 19950179, 2010). "This could be the reason why the inhibition of MyD88 failed to mitigate the severity of colitis, as evaluated by DAI, HS, and several proinflammatory cytokines, including IL-1β, IFN-γ, and TNF-α." (PMID 38946731, 2024). "The data suggested that further inhibition of the NLR signaling pathway in TJ5-treated DSS-colitis mice could ameliorate colitis severity, which was not improved by MyD88 inhibition with TJ5 alone." (PMID 38946731, 2024). "Our study suggests that inhibiting MyD88 with TJ5 may not improve the severity of colitis in an acute DSS-induced colitis model, even though the activation of the proinflammatory NF-κB pathway was partially restricted." (PMID 38946731, 2024). "However, research using the Myd88-knockout mouse model, the antibiotic-induced colitis model, and the dextran sulfate sodium (DSS)-induced colitis model all led to the same conclusion: CX3 CR1+ dendritic cells show a great ability to migrate to mLNs and present antigens." (PMID 39144142, 2024). "Further blockade of the NLR signaling pathway in MyD88-suppressed mice could ameliorate the severity of colitis that was not improved by MyD88 inhibition." (PMID 38946731, 2024). "No considerable difference of colitis parameters was observed between MyD88−/− mice and WTcontrols." (PMID 38946731, 2024). "The beneficial effects of rTs-gal on colitis may be achieved by controlling the intestinal flora and bacterial functions, which may reduce the generation of LPS and suppress the expression of TLR4, MyD88, and NF-κB." (PMID 38172977, 2024). "Expression of NF-κB, TLR4, Myd88, and downstream molecules such as TNF-α, IL-6, and IL-1β was effectively reduced by SGP-H, which improved the secretion of anti-inflammatory cytokines including IL-20 and IL-10 in the colon tissue and serum of DSS-induced colitis mice." (PMID 37836386, 2023). "Nec-1, RIP3, inhibitor has a therapeutic effect on colitis mice via promoting ZO-1 expression and the proportion of Treg cells, and alleviating the secretion of inflammatory cytokines and necroptosis of mouse intestinal epithelial cells by inhibiting TLR4/MyD88/NF-κB and ROS generation." (PMID 35346043, 2022). "In conclusion, GLE supplementation promotes DSS-induced colitis recovery by regulating inflammatory cytokines, preserving the intestinal mucosal barrier, positively modulating microbiota changes, and positively influences immune response in TRAF6/MyD88/NF-κB signaling pathways." (PMID 36553765, 2022). "Therefore, in our study, a large number of in vivo and in vitro experiments have been demonstrated that melatonin-mediated MT2 inhibits aeromonas-goblet cell interactions to restore the level of MUC2 production via the LPS/TLR4/MyD88/GSK-3β/ROS/NF-κB loop, further improving colitis in SD mice." (PMID 35355860, 2022). "Absence of disease in double-deficient (NEMOIEC−KO + MYD88−/−) mice, lacking NEMO and the important bacterial sensor myeloid differentiation primary response 88 (MYD88), supported a role for the gut microbiota in driving colitis." (PMID 36012618, 2022). "Taken together, our results indicate that goblet cell modulation by IL-33 might be directly influenced by IL-33 itself or by other non-T cells, such as macrophages, but independently of the MyD88 pathway during colitis." (PMID 28404987, 2017). "It was shown that azoxymethane (AOM)-DSS-induced colitis triggered up-regulation of Iqgap2 expression in MyD88-/- colons and not in the similarly treated WT controls, suggesting that MyD88 or its downstream effectors may negatively regulate IQGAP2 expression." (PMID 26047140, 2015).
colitis (continued). "Similarly, MyD88-dependent signaling by radioresistant, non-myeloid cells has been shown to provide protection from inflammation in a chemically induced model of colitis via enhanced signaling through the epidermal growth factor receptor (EGFR)." (PMID 25346729, 2014). "While IL-1R signaling is key to many of the changes in IEC function and proliferation seen in these mice, there are other aspects of their exaggerated colitis (inflammation, commensal depletion etc) that are at least partially IL-1R independent but are still MyD88 dependent (not shown)." (PMID 23950714, 2013). "Regarding colon carcinogenesis not driven by colitis, it has been reported that the genetic ablation of MyD88, protects mice from colon carcinogenesis, thus suggesting that Tlrs may favor carcinogenesis." (PMID 22242189, 2012). "For example, mice lacking TLR2 or TLR4 or the MyD88 adaptor protein involved in TLR signal transduction, exhibited increased susceptibility to the chemically induced dextran sulfate sodium (DSS) model of colitis 13–15." (PMID 19950179, 2010). "Quinic acid treatment could alleviate the symptoms of dextran sodium sulfate (DSS)-induced colitis in mice, maintain the intestinal barrier, down-regulate the expression of inflammatory factors such as IL-1β and TNF-α, and inhibit the activation of the MyD88/NF-κB signaling pathway." (PMID 40647020, 2025). "The effectiveness of similar polysaccharides like ASP-Ag-AP and GLP in reducing colitis via the TLR4/MyD88/NF-κB pathway suggests that EPS-LM, which also exerts anti-inflammatory effects through this pathway, may have comparable protective benefits against inflammatory conditions such as colitis." (PMID 39599671, 2024). "In addition, to some degree, different levels of Asp administration decreased the gene expression of TLR4 and MYD88 as well as the TNF-α and IL-6 contents in the UC mice, suggesting that Asp could alleviate colitis in mice by regulating the secretion and expression of inflammatory cytokines." (PMID 36145082, 2022). "However, α-TREM-1 treatment did not alleviate colitis in Tlr4- and Myd88-KO mice." (PMID 33767714, 2021). "Indirect blocking of NF-κB activation through lack of the MyD88 gene in intestinal epithelial cells, made the DSS-induced colitis worse in mice." (PMID 35844499, 2022). "Meanwhile, DSS-induced colitis promotes the expression of glycoprotein 2 (GP2), a specific marker of M cells, in the colon of wild-type (WT) mice but not in MyD88−/− mice." (PMID 35051090, 2021). "In contrast, no changes in colitis severity was detected in mice harboring a disrupted TLR2 and MYD88 gene." (PMID 23372731, 2013). "Mice lacking MyD88, a critical innate immune signaling molecule, exhibited altered severity to DSS-induced colitis indicating an important role for innate immune signaling in intestinal injury." (PMID 22853702, 2012). "Moreover, in MyD88−/− mice, DSS induced colitis but failed to upregulate mRNA levels of M cell specific genes in the colon." (PMID 35051090, 2021). "However, HnAb treatment decreased the mRNA expression of TLR4 and MyD88, but not that of TLR2, TLR9, compared to vehicle-treatment in DSS-induced colitis mice." (PMID 33193406, 2020). "In addition, curcumin treatment suppresses MyD88 protein expression in the colon but not in the liver and is independent of DSS induction of colitis." (PMID 31026259, 2019). "Results of these investigations demonstrate that FXR activation effectively rescued TLR9−/− and MyD88−/− mice from colitis induced by TNBS, strionlgly indicating that the FXR signaling pathways lies downstream to TLR9 and MyD88 and is conserved in mice lacking the expression of these genes." (PMID 23372731, 2013).
Sepsis (151 papers, 2007 to 2026). Sepsis is defined as life-threatening organ dysfunction caused by a dysregulated host response to infection. "Studies have suggested that TLR4, associated with its downstream molecule MyD88, plays an important role in inflammation during sepsis." (PMID 40148079, 2025). "Specifically, Myd88 influences Toll-like receptor signalling pathways and high levels of Myd88 are associated with greater sepsis mortality." (PMID 39855935, 2025). "Our previous work confirmed that NETs induced METTL3‐mediated m6A modification of GPX4 via TLR9/MyD88/NF‐κB pathway in sepsis‐associated lung injury." (PMID 37715457, 2023). "MyD88 deficiency improved resistance to polymicrobial sepsis, indicating that both MyD88-dependent and MyD88-independent antibacterial mechanisms exist." (PMID 36389170, 2022). "The TLR4 downstream adaptor MyD88 is a key adaptor in interleukin-1 receptor (IL-1R) signaling, and a study demonstrated that MyD88-deficient mice exhibit resistance to LPS-induced sepsis." (PMID 36439213, 2022). "The real-world GSE24327 data were generated from samples recovered from spleens 12 hours after the CASP-model sepsis in MyD88-deficient and wildtype mice." (PMID 35774781, 2022). "Together, our results provide novel insights into a better understanding of innate immune responses triggered by the CASP-model sepsis in both wildtype and MyD88-deficient mice at the systems-level in a broader vision." (PMID 35774781, 2022). "More specifically, MYD88 activation is a key cause of myelosuppression during sepsis, while TRIF activation has a greater effect on HSCs." (PMID 34356379, 2021). "By contrast, there are reports showing that MyD88-deficient mice are more resistant to polymicrobial sepsis due to reduced systemic inflammation." (PMID 25084278, 2014). "Similar numbers of WT and MyD88-deficient neutrophils were found in the peritoneal lavage of WT mice after sepsis induction." (PMID 25084278, 2014). "Altogether, the results suggest that the reduction in neutrophil recruitment in MyD88-deficient mice during sepsis is a consequence of the impairment in the production of chemotactic mediators." (PMID 25084278, 2014). "MyD88-deficient mice were susceptible to sepsis because of an impaired local production of chemokines and defective neutrophil recruitment to the infection site." (PMID 25084278, 2014). "It is known that both reduced systemic inflammatory response and organ damage are beneficial in sepsis and it is a rational explanation for the reduced mortality in MyD88-deficient mice in the cited studies." (PMID 25084278, 2014). "Deficiency of MyD88 has been shown to be protective in polymicrobial sepsis, in which especially liver injury was found to be associated with MyD88 dependent signaling." (PMID 25254554, 2014). "Weighardt and colleagues found that MyD88-deficient mice were protected from developing sepsis in a polymicrobial septic peritonitis disease model." (PMID 20981241, 2010). "Notably, BCG-vaccinated neonatal mice exhibited reduced TLR4/MyD88 signaling and suppression of pathways linked to granulocyte migration and recruitment, neutrophil adhesion and movement, compared to sepsis alone." (PMID 40307728, 2025). "In recent years, studies have suggested that sepsis-induced cardiac dysfunction, the major cause of sepsis mortality (70–90%), is caused by myocardial apoptosis mediated by the MyD88 signal pathway that activates and over-expresses a variety of pro-inflammatory cytokines, including TNF-α and IL-6." (PMID 32423469, 2020). "Loss of MyD88 accelerates the progression of secondary sepsis." (PMID 30642901, 2019). "A Turkish study demonstrated the MyD88 SNP -938 C/C genotype was associated with sepsis." (PMID 28840846, 2018).
Sepsis (continued). "We used a model of Klebsiella pneumonia and secondary sepsis in mice that were selectively deficient for MyD88 in specific cell-types that are implicated to be important for host defense mechanisms by use of a tissue specific gene recombination system and bone marrow transfer." (PMID 25254554, 2014). "Similarly, others have also shown the reduction of an inflammatory response in MyD88-deficient mice during polymicrobial sepsis." (PMID 25084278, 2014). "However, the adoptive transfer of WT resident cells into MyD88-deficient mice before the induction of sepsis resulted in the increase of local levels of CXCL2." (PMID 25084278, 2014). "However, here we demonstrate that the abrogation of most TLR signaling, as assessed in MyD88-deficient mice, leads to increased susceptibility to sepsis because of the inability to establish a local inflammatory response." (PMID 25084278, 2014). "MyD88-deficient mice were more susceptible to CLP-induced sepsis than wild-type mice." (PMID 25084278, 2014). "We found that the MyD88-deficient mice were fully protected from damage caused by sepsis." (PMID 22655058, 2012). "However, inflammatory responses during polymicrobial sepsis in mice deficient for MyD88 were markedly reduced implicating the importance of this signal transduction molecule in certain inflammatory scenarios." (PMID 17615075, 2007). "Irisin causes a decrease in TLR4 and MyD88 levels, which could prevent the development of sepsis." (PMID 35784579, 2022). "In addition, MyD88-deficient mice also showed increased bacterial load in the peritoneal cavity and blood, as well as reduced IL-6 levels in the plasma 6 h after severe sepsis induction." (PMID 25084278, 2014). "By targeting Myd88, an essential adaptor molecule involved in immunity, our system demonstrates therapeutic efficacy against septicemia in C57BL/6J mice and improves repeated AAV administration by reducing antibody responses." (PMID 41537395, 2026). "ZDHHC6 knockdown reduces MYD88 palmitoylation and TLR/MYD88 signaling upon activation, making it a potential therapeutic target for sepsis." (PMID 40814339, 2025). "Here, we extend those findings by demonstrating that cilastatin also protects against sepsis-induced AKI via interference with the TLR4/MyD88/NF-κB and NLRP3 signaling pathways, resulting in improved survival." (PMID 40869248, 2025). "In line with findings for TLR4, MyD88, and NF-κB, sepsis significantly increased renal expression of NLRP3 and caspase-1 and its activated form (cleaved caspase-1 protein) compared to controls, as shown through Western blotting." (PMID 40869248, 2025). "Previous studies have shown that PCSK9 enhances TLR4/MyD88/NF-κB signaling and endothelial dysfunction during sepsis." (PMID 41462858, 2025). "The expression of TLRs and mass release of inflammatory mediators through the activation of NF-κB and MyD88 are involved in the pathophysiology of sepsis and in multiple organ dysfunction syndrome (MODS)." (PMID 40076895, 2025). "TLR4, associated with its downstream mediator myeloid differentiation primary response 88 (MyD88), is activated by LPS and regulates inflammation and apoptosis in RTECs during sepsis." (PMID 40148079, 2025). "Overall, LPS-induced extracellular AREG aggravated or triggered macrophage pyroptosis through the EGFR/TLR4/Myd88/NF-κB signaling pathway, providing promising treatment strategies for sepsis." (PMID 40292295, 2025). "For instance, TNFSF14 exacerbated sepsis‐related acute kidney injury via the TLR4/MyD88/NF‐κB pathway and activated the NFκB‐TLR3 pathway to induce acute hepatitis." (PMID 40768619, 2025). "Investigators showed Myd88 inhibition provided preventive protection against sepsis in both Cas9 transgenic mice (mice with Cas9 engineered into their genome) and normal mice." (PMID 39855935, 2025).
Sepsis (continued). "Studies have reported that calycosin can relive sepsis-induced acute lung injury (ALI) by inhibiting the HMGB1/myeloid differentiation factor 88 (MyD88)/NF-κB pathway and activating the NLRP3 inflammasome." (PMID 41463300, 2025). "The results indicate that treatment with rEgAgB had the ability to regulate macrophage polarization possibly through suppressing TLR2 and MyD88 expressions, thus protecting tissues from being injured by the inflammatory storm of sepsis." (PMID 39548530, 2024). "T. spiralis cystatin (TsCys) derived from adult worms also alleviated inflammatory models like sepsis by activating M2 phenotypic macrophages mediated by inhibiting the TLR2/MYD88 signaling pathway." (PMID 39314046, 2024). "Alleviating sepsis through activating M2 phenotypic macrophages mediated by inhibiting the TLR2/MYD88 signaling pathway." (PMID 39314046, 2024). "Collectively, these results suggested that Sptlc2 deficiency decreases LPS-induced inflammation in vivo and ameliorates sepsis symptoms through attenuating MyD88-directed signal transduction." (PMID 39025856, 2024). "The levels of TLR2 and MyD88 were measured in these tissues to determine the involvement of TLR-2/MyD88 in the sepsis-induced inflammatory signaling pathway." (PMID 39548530, 2024). "It has been shown that the overexpression of miR-365-3p attenuated sepsis-mediated MI and inhibited the activation of the NF-κB inflammatory pathway through targeting myeloid differentiation factor 88 (MyD88)." (PMID 38132140, 2023). "Up to now, no study has reported the regulatory effect of MAF on the TLR4/myD88/NF‐κB signaling pathway during sepsis, let alone its effect on the intestinal flora." (PMID 38455195, 2023). "Another study showed that in the sepsis related acute kidney injury cell model established by lipopolysaccharide stimulated HK-2 cells, Myd88 inhibited cell growth and promoted inflammation and oxidative stress (Zhou, Qing & Xu, 2021)." (PMID 37953776, 2023). "Our research shows that sepsis can induce a systemic inflammatory response in mice by activating the TLR4/MyD88/NF-κB signalling pathway, thus increasing the mortality of mice." (PMID 38102579, 2023). "In both datasets, the expression level of AIM2, ELANE, and MYD88 were significantly higher in sepsis patients compared to healthy individuals, while the expression level of CHMP7, GZMB, and NLRP1 were significantly lower." (PMID 36618365, 2022). "Based on the 21 KO MyD88-associated target signaling pathways, we conceptualize the systemic mechanisms underlying the innate immune responses triggered by the CASP-model sepsis." (PMID 35774781, 2022). "calycosin alleviates sepsis-induced ALI in young rats by inhibiting the HMGB1/MyD88/NF-κB pathway and NLRP3 inflammasome activation." (PMID 35720285, 2022). "So the relationship between MyD88 splicing, sepsis, and immunosuppression remains a complicated one, perhaps not surprising given the extreme complexity of this disease." (PMID 36531997, 2022). "Our previous studies reported the involvement of MyD88–NFκB signaling in immunomodulatory effects from MSCs in animal models of sepsis and systemic lupus erythematosus." (PMID 35628107, 2022). "In LPS-induced sepsis, activation of TLR4 causes downstream NF-κB and MAPKs pathways to be activated in a MyD88-dependent manner, thereby enhancing pro-inflammatory cytokines including TNF-α and IL-6." (PMID 36402943, 2022). "As a key molecule to transduce signals from TLR4 to downstream pathways, MyD88 also has crucial roles in sepsis-induced organ injuries." (PMID 35410456, 2022). "The results revealed that monocyte MyD88 protein and p-P65 NFκB protein expression were significantly increased in Lpar3-/- mice with sepsis." (PMID 35464399, 2022). "Our results further confirm that severe infection of bacteria in sepsis stimulates inflammatory immune responses through HMGB1/TLR2/MyD88 activation signal pathway as shown for other helminth-derived proteins." (PMID 33842398, 2021).